PPP2R1A (protein phosphatase 2 scaffold subunit Aalpha)
Diseases named in the same sentence as PPP2R1A in open-access papers (continued):
Sharing a sentence is not in itself a finding about the gene and the disease.
prostate carcinoma (2 papers, 2025). A carcinoma that arises from epithelial cells of the prostate gland. "PPP2R1A and KPNB1 are particularly interesting candidate targets because PP2A activation and KPNB1 inhibition are validated therapeutic approaches in prostate cancer where both SH-BC-893 and FTY720 have demonstrated activity." (PMID 40588551, 2025).
uterine carcinosarcoma (2 papers, 2014 to 2022). A usually aggressive malignant neoplasm arising from the uterine corpus and less often the cervix. "The serine/threonine phosphatase, PPP2R1A, was mutated in one uterine carcinosarcoma." (PMID 25233892, 2014).
uterine neoplasms (2 papers, 2024 to 2025). "Studies on different histologic subtypes of ovarian and uterine neoplasms showed that mutation degree in PPP2R1A were associated with the grade and type of cancer." (PMID 39850502, 2025). "Research on various histologic subtypes of ovarian and uterine neoplasms has demonstrated that the mutation degree in PPP2R1A correlates with the grade and type of cancer." (PMID 39850502, 2025).
Anxiety (1 paper, 2025). Intense feelings of nervousness, tension, or panic often arise in response to interpersonal stresses. "Ppp2r1a haploinsufficiency in forebrain excitatory neurons reduces anxiety level and impairs spatial learning." (PMID 40839403, 2025). "Our research demonstrated that Ppp2r1a haploinsufficiency in forebrain excitatory neurons diminished anxiety levels and impaired spatial learning and memory, highlighting its important role in these neurons." (PMID 40839403, 2025).
autoimmunity diseases (1 paper, 2022). "Otherwise, PPP2R1A may be involved in the regulation of T cell functions in autoimmunity diseases 24,25." (PMID 36186907, 2022).
cardiac hypertrophy (1 paper, 2009). "Consistent with molecular signalling events known to occur under conditions of physiological cardiac hypertrophy, there were three PI3K/AKT signalling pathway molecules (Gsk3b, Nfkbia, and Ppp2r1a) altered in exercised mice and rats." (PMID 20003209, 2009).
dementia (1 paper, 2014). Loss of intellectual abilities interfering with an individual's social and occupational functions. "Among the six PP2A proteins, three proteins (PPP2R2B, PPP2CA, and PPP2R1A) are also listed in the highly ranked proteins in the dementia network, demonstrating their centrality." (PMID 24908109, 2014).
endometrioid tumor (1 paper, 2022). A benign, borderline, or malignant epithelial tumor of the female reproductive system characterized by the presence of glands and/or cysts lined by neoplastic cells that resemble endometrial cells.
glioblastoma (1 paper, 2024). The most malignant astrocytic tumor (WHO grade IV). "Recent studies have also shown the functional impact of PPP2R1A-179 in UCEC (n = 26) and CIC-215 in glioblastomas." (PMID 38473427, 2024).
gynecologic cancers (1 paper, 2019). "PPP2R1A mutations were also reported in type I ECs and other common gynecologic cancers, albeit at much lower frequencies (0–7%)." (PMID 31214504, 2019). "Patient stratification based on PPP2R1A status of the tumor could also be applied to other gynecologic cancer types, even when PPP2R1A mutations are rare." (PMID 31214504, 2019). "We will mainly focus on the potential predictive and prognostic value of PPP2R1A, encoding the Aα subunit of PP2A, which is mutated in up to 40% of type II ECs, while largely being unaffected in type I ECs and other common gynecologic cancers." (PMID 31214504, 2019).
hypertrophic cardiomyopathy (1 paper, 2025). A condition in which the myocardium is hypertrophied without an obvious cause. "Conversely, the PPP2R1A low-expression group showed enrichment in fructose and mannose metabolism, hypertrophic cardiomyopathy, and calcium signaling pathway, among others." (PMID 41327671, 2025).
laryngeal carcinoma (1 paper, 2018). Carcinoma that arises from the laryngeal epithelium. "Among 275 investigated proteins, 12 crucial proteinsare determined that 4 of them can be introduce as a possible biomarker panel includingYWHAZ, PPP2R1A, HSP90AA1, and CALM3 for human laryngeal cancer." (PMID 29755572, 2018). "We choose cutoff 1200 for degree and therefore YWHAZ and PPP2R1A as the toptwo up-regulated genes and also HSP90AA1 and CALM3 as the top two down-regulated genes areintroduced as human laryngeal cancer." (PMID 29755572, 2018). "Finally, a possible biomarker panelincluding YWHAZ and PPP2R1A as the two up-regulated genes and HSP90AA1 and CALM3 as the twodown-regulated genes for human laryngeal cancer is introduced." (PMID 29755572, 2018).
leiomyosarcoma (1 paper, 2023). An uncommon, aggressive malignant smooth muscle neoplasm, usually occurring in post-menopausal women. "However, we did not identify an association between the histological subtype of leiomyosarcoma and gene regulatory heterogeneity in pathways that had PPP2R1A among their major contributors." (PMID 37492373, 2023). "PORCUPINE highlighted genes and TFs that are enriched in driving heterogeneity among leiomyosarcoma patients, including RB1 and PPP2R1A as target genes, as well as the TFs E2F8 and ZNF282, which could potentially be inhibited." (PMID 37492373, 2023).
liver fibrosis (1 paper, 2022). "Studies have demonstrated that specific knockout of the ppp2r1a gene (encoding the PP2A Aα subunit) in mice promotes inflammation and liver fibrosis." (PMID 35933397, 2022).
lung disease (1 paper, 2024). "Direct interactors with the CFTR protein, including SNAP23, KRT19, PPP2R1A, and PPP2R4 proteins, were also identified as lung disease modifiers in a longitudinal study." (PMID 40225935, 2024).
lung squamous cell cancers (1 paper, 2016). "Gain-of-function mutations of PPP2R1A (Haesen and Sablina unpublished) were found in uterine and lung squamous cell cancers." (PMID 27557495, 2016).
metastatic cancer (1 paper, 2016). A carcinoma which has spread from the original site of growth to another anatomic site. "PPP2R1A (E370X), SETD2 (I1608V), SMAD4 (G382T), and AR splicing site mutations were specific to liver metastatic cancer." (PMID 27023146, 2016).
metastatic tumors (1 paper, 2016). "Comparison of the primary and metastatic tumors revealed that PPP2R1A (E370X), SETD2 (I1608V), SMAD4 (G382T), and AR splicing site mutations may be specific to liver metastatic cancer." (PMID 27023146, 2016).
mucoepidermoid carcinoma (1 paper, 2022). A carcinoma morphologically characterized the presence of cuboidal mucous cells, goblet-like mucous cells, squamoid cells, cystic changes, and a fibrotic stromal formation. "The mucoepidermoid carcinoma harbored a BAP1 Q40 and a PPP2R1A R260C mutation." (PMID 35565429, 2022).
myelomeningocele (1 paper, 2020). Myelomeningocele is the most severe form of spina bifida. "PPP2R1A on chromosome 19 also associated with myelomeningocele in the MA population." (PMID 32970752, 2020). "PPP2R1A is another novel gene association with myelomeningocele." (PMID 32970752, 2020).
myopia (1 paper, 2023). "SFRP3 and PPP2R1A were enriched in the WNT pathway, which accompanied the progression of myopia." (PMID 38087190, 2023).
neural tumors (1 paper, 2025). "Overall, by comparing to PA, we identified subtype-specific pathways in neural tumors: PAK signaling (PTPRD and PDGFRB) in GBM, regulation of CFTR activity pathway (PPP2R1A, RABEP1) in MBL, and ERK signaling (IRS4 and ATM) in NBL." (PMID 40768543, 2025).
neuroblastoma (1 paper, 2014). Neuroblastoma (NB) is the most common solid, extracranial childhood tumor. "siRNA mediated knockdown of PPP2R1A (Protein phosphatase 2 (formerly 2A), regulatory subunit A, alpha isoform) reported to decrease α-syn S129 phosphorylation levels in neuroblastoma derived cells." (PMID 25426138, 2014).
optic atrophy (1 paper, 2023). A disorder characterized by loss of optic nerve fibers. "We report an individual with a novel PPP2R1A variant and PCH in the context of a stable clinical condition, and not showing other typical features of PPP2R1A-associated NDD, while presenting optic atrophy and peripheral neuropathy." (PMID 37762002, 2023).
ovarian serous cystadenocarcinoma (1 paper, 2016). A malignant serous cystic epithelial neoplasm arising from the ovary. "However, PPP2R1A mRNA expression level is not elevated in various stages of ovarian serous cystadenocarcinoma in the TCGA database, indicating that PPP2R1A expression is only increased in high-grade carcinomas." (PMID 27272709, 2016).
papillary adenocarcinoma (1 paper, 2008). A morphologic variant of adenocarcinoma. "In contrast, those promoting Ca++ desensitization, such as the MLCPs (Ppm1a, Ppm1g, Pp2r2d, Ppp2r1a, Ppp1 catalytic subunit and Cdc42), were more highly expressed in the papillary adenocarcinoma tumors." (PMID 18811984, 2008).
primary immunodeficiency (1 paper, 2025). "Regarding GSEA pathway scoring, the PPP2R1A high-expression group showed enrichment in antigen entry and presentation, lysine degradation, lysosomes, DNA replication, and primary immunodeficiency." (PMID 41327671, 2025).
primary liver cancer (1 paper, 2025). "Moreover, certain genetic variants in PPP2R1A are linked to an elevated risk of primary liver cancer." (PMID 40251453, 2025).
prostate tumors (1 paper, 2025). "Given that PPP2R1A and these importins are ubiquitously expressed and that JUN, YAP, MYC, and NF-κB drive many different types of cancer, sphingosine-like drugs should be effective across cancer classes, not just against prostate tumors." (PMID 40588551, 2025).
pulmonary fibrosis (1 paper, 2023). Chronic progressive interstitial lung disorder characterized by the replacement of the lung tissue by connective tissue, leading to progressive dyspnea, respiratory failure, or right heart failure. "Compared with the control group, the BLM-induced pulmonary fibrosis group exhibited significantly higher expression of Fmod and Tgfbr2 mRNA; in contrast, the mRNA expression levels of Bambi, Skp1, Zfyve9, Zfyve16, Ppp2ca, Ppp2r1a, Ppp2r1b, Rps6kb1, and Rps6kb2 were markedly lower." (PMID 38259493, 2023).
thyroid cancer (1 paper, 2025). "This approach identified significant dependencies on key genes/proteins such as KRAS, NRAS, PABPC1, PPP2R1A, STAG2, and BRAF in thyroid cancer cell lines, underscoring their potential as critical therapeutic targets." (PMID 40297138, 2025).
cancer (64 papers, 2013 to 2025). A tumor composed of atypical neoplastic, often pleomorphic cells that invade other tissues. "In this study, we observed that PPP2R1A levels were lower in all cancer types compared to healthy cell lines, which is consistent with the literature suggesting that PPP2R1A levels are associated with the clinical stages and prognosis of various cancer types." (PMID 39850502, 2025). "Subsequently, a scatter plot generated using the most relevant algorithm presented the correlation between PPP2R1A gene expression and cancer-associated fibroblasts across diverse malignancies." (PMID 41409293, 2025). "Collectively, our findings provide novel insights into the mechanism underlying nelfinavir-induced cancer cell death and validate PPP2R1A as a promising therapeutic target for LUAD." (PMID 38654331, 2024). "Towards the identification of new candidate cancer driver mutations within this module, we focused on the p.Arg258Cys mutation in the PPP2R1A protein." (PMID 36945530, 2024). "We then isolated stable transfectants from the PPP2R1A KO cell line that expressed FLAG-GFP PPP2R1A fusion proteins, either wild type or harboring the frequent cancer-associated mutations, P179R, R183W, or W257C." (PMID 37322026, 2023). "The mutations in PPP2R1A have been identified in multiple cancers, but the effects of these mutations on PP2A function need to be fully elucidated." (PMID 34076143, 2021). "Another intriguing fact is that these PPP2R1A mutations almost always occur at the same residues across several cancer types, forming so called hotspot mutations." (PMID 31214504, 2019). "PPP2R1A mutation has been observed at high frequency in endometrial serous carcinoma and it promotes cancer cell growth." (PMID 29444159, 2018). "Genetic variants in PPP2R1A or PPP2R5E had been reported to be associated with risk of human cancers." (PMID 24204789, 2013). "Notably, in one study, these functionally more disruptive variants were also found in the Catalog of Somatic Mutations in Cancer (COSMIC) or affected at the same amino acid as cancer-associated PPP2R1A variants." (PMID 39850502, 2025). "Mutations of PPP2R1A occur in several cancers to promote malignant cell growth." (PMID 36292952, 2022). "Interestingly, however, the few number of PPP2R1A mutations that are present mainly occur at the hotspot residue p.R183, which is most frequently affected across all cancer types." (PMID 31214504, 2019). "Recently, a few studies have investigated the association between PPP2R1A variants and cancer risk." (PMID 23555712, 2013). "Finally, the response of type II ECs to SMAPs could also be dependent on the PPP2R1A mutational status of the cancer cells, especially since these SMAPs bind to the Aα subunit in close proximity to the PPP2R1A hotspot mutations." (PMID 31214504, 2019). "Therefore, the objective of this study was to determine whether PPP2R1A mutations contribute to cancer progression through affecting cell proliferation, migration, and PP2A phosphatase activity." (PMID 27272709, 2016). "Using the Xiantao online tool to assess the expression levels of PPP2R1A mRNA, we detected a significant increase in PPP2R1A expression in 26 cancers." (PMID 41409293, 2025). "Further studies using standardized assays on well-characterized patient samples are warranted to elucidate PPP2R1A’s role in cancer." (PMID 41409293, 2025). "The findings suggest that propolis holds promise as a potential cancer therapy by increasing PPP2R1A levels, a key molecule in cancer treatment." (PMID 39850502, 2025). "In this study, we investigated the effect of propolis as a potential stimulant on PPP2R1A levels, targeting various cancer cell lines." (PMID 39850502, 2025). "Our findings indicated that propolis increased the PPP2R1A levels and apoptosis markers in cancer cell lines." (PMID 39850502, 2025).
cancer (continued). "This situation suggests that propolis shows promise in cancer treatment and demonstrates its ability to increase PPP2R1A levels, thereby affecting the target molecule in cancer therapy." (PMID 39850502, 2025). "In this study, the inducible effect of propolis on PPP2R1A levels, identified as a new target for cancer treatment, was demonstrated for the first time." (PMID 39850502, 2025). "Despite extensive evidence linking PPP2R1A to various cancers, its specific role in GC remains to be elucidated." (PMID 40251453, 2025). "Before addition of propolis, PPP2R1A levels were lower in all cancer cell types than those in control cells (WI-38)." (PMID 39850502, 2025). "We utilized various bioinformatics tools to assess the expression of PPP2R1A across multiple cancer types, revealing its upregulation in LUAD." (PMID 41409293, 2025). "In this study, we aimed to investigate the possible induced effect of propolis on PPP2R1A in cancer cells in terms of SW-620, DU-145, PC3, MCF-7 cancer cell line, and WI-38 healthy cell line." (PMID 39850502, 2025). "Somatic mutations in PPP2R1A and PPP2R1B are frequently detected in cancer, and functional haploinsufficiency promotes tumorigenesis." (PMID 38502192, 2024). "Endometriotic lesions also harbour cancer driver mutations such as PIK3CA, PTEN, ARID1A, KRAS, PPP2R1A, and β-catenin (CTNNB1)." (PMID 38893278, 2024). "In recent years, there has been a growing body of evidence indicating the presence of somatic mutations in cancer-associated genes including ARID1A, PIK3CA, KRAS, or PPP2R1A in endometriotic lesions." (PMID 38600147, 2024). "This can also be used to explain why the in vivo anti-cancer effect of LB-100/anti-PD1 was worse than that of anti-PD1 combined with Ppp2r1a gene knockdown in mouse cancer cells." (PMID 34911954, 2021). "In summary, we demonstrated that carcinogen-induced cancer arises from Lgr5+ crypt stem cells in Ppp2r1a−/− mice." (PMID 31905853, 2019). "PPP2R1A can bind to T antigen (TAg) from both SV40 and polyoma virus, thus providing evidence that PPP2R1A can function as cancer relevant genes." (PMID 27272709, 2016). "Taken together, these results indicate that the expression level of PPP2R1A is highly increased in various human carcinomas and the overexpression of the PPP2R1A-WT promotes SKOV3 cell proliferation." (PMID 27272709, 2016). "In conclusion, compounds that target PPP2R1A and importins could show therapeutic potential in treatment-resistant tumors and across cancer classes." (PMID 40588551, 2025). "We analyzed PPP2R1A expression across cancers using the Xiantao Academic Online tool and TCGA data." (PMID 41409293, 2025). "In our study investigating the relationship between propolis and cancer cell lines' PPP2R1A and apoptosis, the treatment with propolis supports our findings positively, as it increases all apoptosis markers in SW-620 and DU-145 cells compared with cells without propolis." (PMID 39850502, 2025). "Previous studies have found that PPP2R1A acts as a tumor suppressor gene in various cancers." (PMID 41409293, 2025). "Synthetic lethal approaches being investigated in tumor-agnostic studies include PARP inhibitors for BRCA1/2- or ATM-mutant cancers; ATR inhibitors for ATM-mutant cancers; and PKMYT1 inhibition for solid tumors with CCNE1 amplification, FBXW7 loss, and PPP2R1A mutations (NCT04855656)." (PMID 38938274, 2024).